COL1A1 (collagen type I alpha 1 chain)
Diseases named in the same sentence as COL1A1 in open-access papers (continued):
Sharing a sentence is not in itself a finding about the gene and the disease.
tumor (continued). "COL1A1 and COL1A2 are two members of Type I collagen, interestingly, both of COL1A1 and COL1A2 are dysregulated in several cancers and involved in tumor invasion and progression." (PMID 34399848, 2021). "Tumor exosomes typically trigger multiple signalling pathways, and we found that MDA PCa 2b exosomes induced drastic degradation of COL1A1 and Type I collagen in the bone ECM after bone marrow education through tail‐vein injection of the exosomes for 4 weeks." (PMID 33489015, 2021). "In the current research, we concluded that circ_0004370 served as a tumor promoter to activate cell viability, cloning, migration and invasion, and EMT process and restrain cell apoptosis via miR-1301-3p/COL1A1 axis." (PMID 33506107, 2021). "Thus, COL1A1 might play a tumor‐promoting role in PRCC by activating Wnt signaling." (PMID 34598322, 2021). "We previously showed that collagen (COL1A1 and COL3A1) mRNAs are increased in tumor tissues from CRC patients compared with normal tissue adjacent to the tumor." (PMID 34966673, 2021). "The key genes COL1A1, COL4A1, COL5A2 belong to the collagen family, which is a constituent of the ECM component of tumors, and is closely related to tumor proliferation, invasion, drug resistance, and prognosis 7,40-46." (PMID 33976737, 2021). "To study DEspR-Col1A1 co-expression in vivo, we examined tumor sections from Panc1-CSC derived xenograft (CDX)-PPC nude rats by immunofluorescence (IF) using human-specific DEspR (7c5) and human/rat reactive Col1A1 fluorescently labeled antibodies." (PMID 33853558, 2021). "The results revealed that COL1A1, COL4A1, COL12A1, and PDGFRB were all negatively correlated with tumor purity." (PMID 35111208, 2021). "Our results showed that the hub genes COL1A1, THBS2, and SPP1 were also able to alter cellular components in the tumor microenvironment, and that they had an axial relationship with PD-L1 expression." (PMID 33345281, 2021). "Genes that encoded extracellular matrix (ECM) components, such as COL1A1, COL1A2, LUM and FN1, were specifically expressed by fibroblasts, suggesting that the ECM in the NPC microenvironment was highly complex and might interact with surrounding tumor and stromal cells via integrin signaling." (PMID 33750785, 2021). "In the tumor stroma, the IHC expression of SPARC and COL1A1 was significantly higher in the group with BM than that in the group without BM (p < 0.001 for both)." (PMID 34503278, 2021). "Both the PCOLCE and mut COL1A1 experiments supported the notion that BMP1, with help from PCOLCE, cleaves procollagen I to stimulate its deposition, which leads to suppression of tumor growth and metastasis." (PMID 33879793, 2021). "The result of this rearrangement is the upregulation of COL1A1-PDGFB fusion proteins that are processed to form mature PDGFB and then to activate PDGFRB to form an autocrine loop, rendering tumor cell proliferation and survival dependent on PDGFRB signaling." (PMID 34362454, 2021). "We found that COL1A1 and CD276 showed significantly higher expression in tumor sites than in the adjacent non-tumor samples." (PMID 33850663, 2021). "The expression of COL1A1, COL4A1, COL12A1, and PDGFRB were all negatively correlated with tumor purity." (PMID 35111208, 2021). "After adjusting the analysis by tumor purity, we found that the expression levels of COL1A2, COL1A1, COL3A1, ZNF469 and Periostin (POSTN) were significantly correlated with tumor purity in ESCA." (PMID 33543230, 2021). "Collagen type I alpha 1 chain (COL1A1), one of the hub genes, is a component of the extracellular matrix and is critical for tumor microenvironment." (PMID 34395525, 2021). "The GS value of ANGPT2 to tumor grade was 0.909, P= 0.006 (SERPINE1, P= 0.025; HS3ST2, P= 0.103; COL1A1, P= 0.040; COL5A2, P= 0.006)." (PMID 33758610, 2021). "In order to assess COL1A1 correlation with CD276, we analyzed COL1A1 and CD276 expression in tumor sites and the adjacent non-tumor samples." (PMID 33850663, 2021).
tumor (continued). "Cell viability and migration assays showed that silencing CTCF, COL1A1, and COL1A3 inhibited the growth and migration of GC tumor cells." (PMID 33665169, 2020). "The quantification results suggested that COL1A1, COL3A1, SPP1, and THBS2 protein levels were significantly increased in GC tumor tissues compared to normal adjacent tissues." (PMID 33665169, 2020). "qRT-PCR results showed that the mRNA expression of COL1A1, IGF1, COL5A1, CXCL12, PTEN, and SPP1 were also significantly differently expressed in normal samples and tumor samples." (PMID 32641130, 2020). "The violin plot showed the metastasis-related genes were higher expression in LUAD tumor tissues, but only LAMC2, THBS2, ITGB4, COL1A1 and FLNC showed positively correlated with poorer survival of LUAD and the expression level of GPR115." (PMID 33330053, 2020). "To validate the results from RNAseq, we measured expression of six genes (COL1A1, FN1, MMP2, TFPI2, CDK6, and CDK4) that were significantly up-regulated in tumor cells compared to normal epithelium by RT-qPCR." (PMID 33142242, 2020). "We found higher levels of COL1A1 and LOX in tumor tissues compared with NTs, which resulted in more significant paired tissues." (PMID 31906302, 2020). "The collagen family (COL1A2, COL1A1, COL6A3, and COL5A1), DCN, FBLN1, and POSTN were the most abundant components of the tumor ECM." (PMID 33613617, 2020). "Among these genes, COL1A1, COL1A2, FN1 and COL5A2 were considered as perspective effective targets that play prominent roles in the development and recurrence of the tumor, including STAD." (PMID 33193601, 2020). "COL1A1 and COL3A1 mRNA expression was significantly increased in tumor tissue compared to adjacent non-tumor tissues in colons from CRC patients (P < 0.0001 and P < 0.03)." (PMID 32171282, 2020). "With the gene ontology analysis, multiple genes involved in cell migration, adhesion and proliferation, as well as angiogenesis regulation, were significantly upregulated in tumours expressing EGFR and COL1A1." (PMID 32901137, 2020). "To investigate the COL1A1 expression profile in HCC and non-tumor liver tissue samples, we used the RNA sequencing and microarray gene profiling data (GSE14323/GPL571, GSE3500, GSE14520 and GSE6764) from GEO and TCGA." (PMID 31181620, 2019). "Once PDGFB is cleaved from the COL1A1-PDGFB chimeric protein, it stimulates tumor cells to go into an autocrine fashion, thus, leading to proliferation transformation." (PMID 31692830, 2019). "Recombinant TGF-β1 or tumour cell conditioned medium (TCM) elevated α-SMA, calponin 1 and collagen 1 A1 (COL1A1) amount on mRNA and protein level in MSC." (PMID 31409840, 2019). "Primary MSC isolated from human bone marrow were differentiated by TGF-β1 and tumour-cell conditioned medium to myofibroblasts with induced expression of the differentiation markers α-SMA, calponin 1 and COL1A1." (PMID 31409840, 2019). "HK2 gene was significantly and positively correlated with tumor size, whereas PFKFB3 was significantly and positively correlated with COL1A1, COL3A1, and HAS2 genes in TN." (PMID 31428701, 2019). "The COL1A1-PDGFB fusion gene, exhibit growth factor activity, this furthers on the proliferation on tumor cells." (PMID 31692830, 2019). "Highly interrelated nodes, such as COL1A1, COL1A2, POSTN, ADAMTS4, and CD34, have been reported to regulate the tumor microenvironment and promote the growth, angiogenesis, and invasion of malignancies." (PMID 31480381, 2019). "In particular, expression of Col1a1, the gene for type 1 collagen and the substrate for FAP, was significantly higher in the 4T1 tumours." (PMID 30054470, 2018). "This degree of deletion resulted in a significant reduction in tumor size when compared with tumors from KrasFRT-STOP-FRT-G12D; p53FRT/FRT; Col1a1+/+; Ng2/Cspg4f/f mice." (PMID 29196603, 2018).
tumor (continued). "We first validated expression of COL1A1, COL1A2, and COL3A1, in OSCC fibroblast pairs isolated from tumor or its adjacent stroma, as well as in two OSCC tumor cell lines, CAL27 and HSC-3, using quantitative PCR." (PMID 27128408, 2016). "PyMT/Col1a1 mice had larger tumors compared to PyMT mice and COX-2 inhibition with celecoxib diminished tumor growth only in collagen-dense tumors." (PMID 27000374, 2016). "ECM-receptor interaction and focal adhesion pathways were closely related to tumor invasion and metastasis, in which three proteins of ITGA2, COL1A1 and COL11A1 were also behaved up-regulation trend in cancer, except FLNC." (PMID 27626164, 2016). "As was consistent with the qRT-PCR results, SPP1, COL1A1 and NT5E proteins were up-regulated, while the expression of HTRA1 and ANGPT1 were down-regulated in the tumor compared with ANPT groups (n = 29)." (PMID 27690016, 2016). "This included EC-specific proteins (e.g. COL1A1, FBN1), tumour-specific proteins (e.g. ITGB1) and proteins up-regulated in both cell types (FN1, THSB1, CD44, ITGA4, CTGF)." (PMID 27049916, 2016). "Overall, we found that β-NGF expression was higher in the tumor epithelial compartment than in the stroma, and that there was more stromal β-NGF in PyMT/Col1a1 tumors compared to PyMT tumors." (PMID 27000374, 2016). "Those genes reportedly involved in tumor cell adhesion, gap junction and ECM, such as CHD1, Cx26, Cx43, Cx45, COL1A1, FN1, LOX, ITGB1 and LAMA4, were also up-regulated following 3D cultures." (PMID 26055407, 2015). "Seven of the twelve differential genes found amongst individual tumor ANOVA analyses were common to the linear discriminant gene profile (LD-p54): ANGPLT4, COL1A1, GP2, GPR57, LAMB3, PCDHB9, and PTGER3." (PMID 15836779, 2005). "Enteric glial cells had fewer potential crosstalk genes, with top regulatory factors ANXA1, TIMP1, and HLA-A, and target genes such as COL1A1 and COL3A1, which may support tumor structure and growth." (PMID 40145096, 2025). "Previous studies have described interactions between COL1A1 and CD44, which may relate to the regulation of stemness and invasiveness in several tumor types." (PMID 40851082, 2025). "Collagen Type I Alpha 1 Chain (COL1A1) and Lysyl Oxidase (LOX) were included as they were upregulated across the three solid stress compression and are important in modulating the tumour microenvironment as well as promoting cancer migration." (PMID 40371393, 2025). "Single-cell sequencing analysis indicated that COL1A1 is predominantly expressed in cancer stem cells in KIRC, suggesting that its role in tumor progression may extend beyond ECM structural support." (PMID 40851082, 2025). "In this sense, the substantial increase in COL1A1 and other ECM remodelling-related genes, such as MMP9 and TNC, after IL-36γ stimulation in HT- 29 cells underscores the role of this cytokine in modulating the tumour microenvironment." (PMID 40268791, 2025). "We then validated the inhibitory effect of these combinations by performing western blot on tumor tissues and cultured cells treated with the same conditions as in vivo experiment and identified the similar reduction of ITGB4 and COL1A1." (PMID 40386428, 2025). "Specifically, in FOXL2+COL1A1− cells, we examined expression of other AGCT tumor markers such as SF1, calretinin, and inhibinα, whereas in FOXL2+COL1A1+ cells, we also examined expression of stromal markers, including αSMA, vimentin, S100A4, PDGFRa, PDGFRb, and FAP." (PMID 41042551, 2025). "To validate the colocalization of STEAP4 and TFE3 in PCa patients, we applied in situ multi‐color immunofluorescence staining using antibodies against COL1A1, STEAP4, and TFE3, and observed STEAP4 and TFE3 double‐positive fibroblasts among the stromal cells within the tumor." (PMID 40917018, 2025). "Finally, ECM and fibrosis-related molecules (COL1A1, COL4A1, COL6A3, fibronectin, and LAMC1) were elevated, closely mimicking the desmoplastic tumor microenvironment of HCC." (PMID 41149589, 2025).
tumor (continued). "KEGG pathway enrichment analysis indicated that COL1A1 may influence the PI3K/Akt signaling pathway, which is known to be involved in tumor cell proliferation, migration, invasion, and EMT regulation." (PMID 40851082, 2025). "The upregulation of COL1A1 suggests that IL-36γ plays a pivotal role in creating a supportive environment for tumour progression by altering the composition and structure of the ECM, thereby promoting tumour cell invasion and migration." (PMID 40268791, 2025). "COL1A1 serves as a classical marker for normal fibroblasts, while ACTA2 is a common CAF marker, typically employed to identify activated fibroblasts actively shaping the tumor microenvironment." (PMID 41584584, 2025). "To determine whether 015s similarly alleviates tumour fibrosis in vivo, we evaluated α-SMA, FAP, and COL1A1 expression in EMT-6 tumours by Western blotting." (PMID 40806691, 2025). "Future studies could explore whether ER/PR signaling in FOXL2+COL1A1+ cells modulates ECM composition and mechanical properties in AGCTs, potentially influencing tumor recurrence or therapy response." (PMID 41042551, 2025). "In addition, shared hub genes across EAC and ESCC—such as COL1A1, SPARC, and MMP1—were enriched in ECM organization and cell adhesion processes, highlighting convergent tumor–stroma interactions." (PMID 40872572, 2025). "EGFR and IDH1 were highly expressed in tumor cells, FAP and COL1A1 were confined to fibroblasts, CD68 and ITGAM marked macrophages, PECAM1 and CDH5 identified endothelial cells, OLIG2 and MOG were specific to oligodendrocytes, while CD4 and CD3D defined T-cell subsets." (PMID 41208987, 2025). "Notably, the fibrillar collagen COL1A1, which is one of the most abundant ECM proteins secreted during tumorigenesis, cooperates to increase tumor stiffness, alter TIME organization, and enhance MMP activity." (PMID 39858054, 2025). "Notably, several genes involved in cell cycle regulation (CCND2, CDKN2A/C), tumor microenvironment (COL3A1, COL1A1), and growth factor signaling (FGF18, ERBB2) showed significant upregulation with fold changes ranging from 1.5 to 2.0." (PMID 41419500, 2025). "This gene fusion product, COL1A1-PDGFB, leads to tumor cell proliferation." (PMID 41393578, 2025). "Fibroblasts around tumor nests may form rigid stroma with HA by promoting the expression of COL1A1 and CTGF, which can form a barrier that surrounds tumor cells and limits access to the tumor by immune cells." (PMID 39858106, 2025). "Immunoblotting results of tumor tissues from different treatment groups confirmed that IR‐LND@Lip effectively downregulated the expression of PD‐L1/TGF‐β dual immune proteins, concurrently leading to a reduction in the expression of the fibrotic marker COL1A1." (PMID 38704675, 2024). "COL1A1 expression may promote angiogenesis by modulating the ECM composition and promoting the secretion of angiogenic factors, thereby supporting tumor growth and metastasis." (PMID 39065771, 2024). "The results suggested that the COL1A1 upregulation in ANH, secretion, and deposition in MLiM may represent a physical barrier for immune cells to infiltrate MLiM tumours." (PMID 39496484, 2024). "As predicted, all three kinds of CAFs showed active EMT, as indicated by strong metalloprotease (MMP2, MMP14, MMP11) and collagen (COL10A1, COL11A1, COL5A1, COL1A1, COL27A1) production, allowing them to breakdown the extracellular matrix and leave the initial tumor location to metastasize." (PMID 37322261, 2024). "Notably, the interaction between COL1A1 and CD44 emerged exclusively in the tumor group, underscoring a tumor-specific communication signature." (PMID 39165361, 2024). "However, other HGs, especially collagen‐related genes, including COL1A1, COL1A2, ITGA2, and POSTN revealed slightly higher methylation in tumor tissue than in normal tissue." (PMID 38639039, 2024).
tumor (continued). "Hallmark pathway analysis confirmed that CTHRC1 and FAP myCAF cluster was most associated with pro-tumorigenic angiogenesis, EMT, hypoxia, and PI3K/AKT/mTOR signaling; and the myCAF (FAP, COL1A1,COL1A3) cluster may be critical for tumor growth and metastasis." (PMID 38525245, 2024). "An independent model, in which human A3B (as a turbo-GFP fusion) is integrated at the Col1a1 locus and expressed inducibly using a R26-integrated tetracycline transactivator, also yields modest A3B expression levels and no significant tumor phenotypes." (PMID 37797615, 2023). "The fact that Collagen signatures exhibit strong predictive power may be because these members themselves (COL1A1, COL4A3, COL5A1, COL11A1, COL22A1) have been reported to predict tumor prognosis." (PMID 37476379, 2023). "CHI3L1, COL1A1, and CXCL14 have been shown to be related to tumor metastasis and invasion." (PMID 37480002, 2023). "Interestingly, we found that the distribution of Scissor+ tumor cells, FABP5+ macrophages, and COL1A1+ CAFs in different subtypes corresponded with their clinical prognostic outcomes." (PMID 37021816, 2023). "In addition, we found a significant increase in the expression of the fibrosis markers collagen type I alpha 1 chain (COL1A1, OMIM 120150) and fibronectin 1 (FN1, OMIM 135600) in the tumor tissues of the proband." (PMID 37752101, 2023). "COL1A1, together with COL1A2, forms type I collagen, which is the major component of the extracellular matrix (ECM) in connective tissues and COL1A1 displayed tumor-promoting effects in various cancer cells." (PMID 37313172, 2023). "And more COL1A1 and BGLAP are expressed in the tumor than in the normal prostate." (PMID 37564213, 2023). "Strikingly, examining the source of collagen gene expression (COL1A1, COL1A2, COL3A1, COL6A1, COL8A1, COL10A1) provided clarity that the majority of genes expressed in the tumor samples represent transcripts of the MSC-related component of the tissue microenvironment." (PMID 36940196, 2023). "Moreover, PECAM1+ cells (ECs) in cluster 8 ECS (COL1A1, COL1A2, COL3A1, PDGFRB, and ACTA2) showed an endothelial-mesenchymal transformation phenotype, which contributed to tumor progression." (PMID 37533434, 2023). "Gene expression of COL1A1, COL1A2, COL6A3, FN1, and THY1 in CAFs as well as COL4A1 and COL4A2 in Angiogenic_EC had a highly significantly positive correlation with the proportion of malignant tumor cells." (PMID 38002057, 2023). "Overall, these data together showed that COL1A1, COL1A2, and COL6A3 are the key molecules that might regulate the tumor pEMT phonotype by interacting with SDC1 and accelerate the malignant progression of cancer patients." (PMID 38002057, 2023). "In these human neoplasms, the macrophage signature correlated with the expression of SNA1, FN1, ACTA2 (αSMA), SPP1 (osteopontin), COL1A1, and VIM, all genes that are specific for active CAFs, indicating that this gene signature is associated with CAF activation." (PMID 37199012, 2023). "Expression of Fn1 and Col1a1 was significantly higher in tumor-bearing bones vs. non-tumor-bearing bones." (PMID 35565211, 2022). "It is also critical to state that we did not identify tumor cells in two of the Col1a1-Krm2-transgenic NSG mice." (PMID 35158823, 2022). "Tumor load in hind limbs was slightly decreased in Col1a1-cre+;Mertkflox/flox mice 3 days after injection, but was not significantly changed after 1 week." (PMID 36509738, 2022). "Besides, we found three genes, including COL1A1, COL3A1, and COL1A2, were significantly upregulated in TCGA BRCA tumor samples compared with normal controls, whereas the other seven genes were not significantly changed in BCa tumor samples (data now shown)." (PMID 35274048, 2022). "Furthermore, significant higher expression of COL1A1 in dLN (vs BME p=0.0075, vs dLU p=0.013) and COL3A1 in BME (vs dLU p=0.007) indicates that the reciprocal production of ECM proteins by tumor cells is also affected by the ECM of the metastatic organ." (PMID 36741736, 2022).